XIAP (X-linked inhibitor of apoptosis)
Diseases named in the same sentence as XIAP in open-access papers (continued):
Sharing a sentence is not in itself a finding about the gene and the disease.
melanoma (79 papers, 2005 to 2025). A malignant, usually aggressive tumor composed of atypical, neoplastic melanocytes. "Elevated XIAP levels are frequently associated with a poor prognosis for patients with various cancers, including melanoma." (PMID 40486906, 2025). "Elevated XIAP levels are commonly associated with a poor prognosis for patients with various cancers, including melanoma." (PMID 40486906, 2025). "X-linked inhibitor of apoptosis (XIAP) has previously been linked to melanoma progression by its anti-apoptotic function in cancer." (PMID 38419052, 2024). "The regulation of this pro-apoptotic pathway by piperine was confirmed in melanoma cells, where piperine downregulated the anti-apoptotic protein human X-linked IAP (XIAP), representing the most characterized among the IAP proteins." (PMID 33256185, 2020). "Several lines of evidence have underlined the critical role of the Smac/XIAP rheostat in induced TRAIL resistance in melanoma cells." (PMID 31083589, 2019). "Significant roles of both c-FLIP and XIAP (chromosome X-linked IAP) have been shown for TRAIL resistance of melanoma cells." (PMID 31083589, 2019). "Above this, we have established a regularized DBN model that was able to predict key players of TRAIL susceptibility correctly and helped to identify XIAP to serve as a potential biomarker for TRAIL treatment responsiveness in mutBRAF melanoma." (PMID 30416750, 2018). "cIAP1 and X-linked IAP (XIAP) are expressed in most of the melanoma cell lines examined with lower cIAP1 levels in PREYER, MeWo, IGR, and MM-LH." (PMID 26355347, 2015). "This family includes X-linked inhibitor of apoptosis protein (XIAP), cellular inhibitor of apoptosis 1 and 2 (cIAP1, cIAP2), melanoma inhibitor of apoptosis (ML-IAP) and survivin." (PMID 25275296, 2014). "Given that chemotherapy response information was not available on most patients in our cohort, we sought to assess the association between high XIAP expression and chemotherapy resistance in melanoma using cell lines." (PMID 17257402, 2007). "In this study we demonstrated that Phenoxodiol treatment of melanoma cells also caused XIAP degradation, cleavage of pro-caspase-2, and activation of caspases -3, -8 and -9 in Carboplatin resistant melanoma cell lines." (PMID 17257402, 2007). "The purpose of the present work was to assess the expression patterns of XIAP in a large cohort of melanoma tumors and benign nevi, and to assess the association of expression with disease stage." (PMID 17257402, 2007). "The finding that the XIAP overexpression is associated with a favorable outcome is contradictory to findings from us and others in different tumor entities, such as esophageal cancer and melanoma." (PMID 36472768, 2023). "Furthermore, it was found that melanoma cells were more susceptible to UVB radiation via XIAP degradation and caspase 3 upregulation." (PMID 21961050, 2011). "We hypothesize that resistance of melanoma cells to chemotherapy is associated with high baseline expression of XIAP." (PMID 17257402, 2007). "Here we assessed whether pretreatment of melanoma cells with Phenoxodiol reverses the baseline resistance to Carboplatin and whether this reversal is associated with XIAP degradation." (PMID 17257402, 2007). "Further studies are needed to determine whether isoflavone analogues and direct XIAP targeting therapies can be used as chemotherapy sensitizers in melanoma patients, and whether XIAP expression levels are associated with response to therapy." (PMID 17257402, 2007). "We further hypothesize that drugs that (directly or indirectly) cause XIAP degradation can result in sensitization of melanoma cells to chemotherapy." (PMID 17257402, 2007). "Furthermore, we demonstrate that Phenoxodiol sensitization to Carboplatin in melanoma is associated with XIAP degradation, although the precise target of Phenoxodiol is still being studied in our laboratory." (PMID 17257402, 2007).
melanoma (continued). "Moreover, owing to the loss of miR-101-3p, melanoma prevents apoptosis by XIAP upregulation." (PMID 38431560, 2024). "We observed that the administration of TRI-03 significantly decreased XIAP protein levels in a dose-dependent manner in melanoma cells, as well as the conversion of LC3-I to LC3-II, which is an indicator of autophagy activation." (PMID 40486906, 2025). "XIAP plays a dual role in apoptosis resistance and inflammation modulation via the NF-κB signalling pathway while also enhancing melanoma cell migration." (PMID 40683913, 2025). "X-linked inhibitor of apoptosis protein (XIAP), a member of the inhibitor of apoptosis (IAP) family, is upregulated in melanoma cells and is associated with resistance to chemotherapy and radiotherapy." (PMID 41550920, 2025). "We analyzed the anticancer mechanisms of these compounds and discovered that pent-1-yn-3-one, an alkynyl-containing compound, effectively reduces XIAP expression in melanoma cells." (PMID 40486906, 2025). "We previously discovered that pent-1-yn-3-one, an alkynyl-containing compound, effectively reduces XIAP expression in melanoma cells." (PMID 40486906, 2025). "Previous studies have shown that both X-linked inhibitor of apoptosis (XIAP) and thioredoxin reductase 1 (TrxR1) participate in the resistance of melanoma to chemotherapy-induced cell death." (PMID 40486906, 2025). "In our preliminary experiments, an alkynyl-containing compound from T. sinensis effectively decreased XIAP expression in melanoma cells." (PMID 40486906, 2025). "This dual inhibition of TrxR1 and XIAP in melanoma cells induces substantial caspase-9/caspase-3 activation, leading to irreversible GSDME-mediated pyroptosis." (PMID 40486906, 2025). "We established melanoma xenograft models in nude mice to evaluate the role of autophagy-mediated XIAP degradation in inhibiting melanoma growth upon TRI-03 stimulation in vivo." (PMID 40486906, 2025). "In this study, the transcript levels of IAP genes including NAIP (BIRC1), BIRC2 (CIAP1), BIRC3 (CIAP2), BIRC5 (Survivin), BIRC6 (Apollon), and XIAP (BIRC4) in UA-treated A-375 melanoma cells were investigated." (PMID 39473730, 2024). "The significant role of the caspase-3 antagonist XIAP in apoptosis resistance in melanoma cells has been shown by siRNA knockdown." (PMID 38542429, 2024). "Downregulation of XIAP in melanoma cells was also seen in response to TRAIL in combination with kinase or HDAC inhibitors." (PMID 38542429, 2024). "ADT-OH inhibits the activation of NF-κB in B16F10 melanoma cells, reduces the expression of downstream target genes of NF-κB pathway (e.g. XIAP, Bcl-2), and induces cell apoptosis via mitochondrial pathway." (PMID 38448410, 2024). "Greater overexpression of XIAP over other IAPs has also been noted in other neuroectodermal cancers such as melanoma and neuroendocrine tumors." (PMID 37874199, 2023). "Mammalian cellular IAP1 (cIAP1), cIAP2, X-linked IAP (XIAP), melanoma IAP, and IAP-like protein 2 contain the RING domain and function as E3-ubiquitin ligases catalyzing both polyubiquitylation and monoubiquitylation." (PMID 35718775, 2022). "These are X-linked inhibitor of apoptosis protein (XIAP), cellular IAP 1 (cIAP1), cellular IAP 2 (cIAP2), IAP-like protein 2 (ILP-2), melanoma IAP (ML-IAP), neuronal apoptosis inhibitory protein (NAIP), Apollon and Survivin." (PMID 35568716, 2022). "The human genome encodes five IAPs proteins in total, which are X-linked inhibitor of apoptosis (XIAP), cellular inhibitor of apoptosis proteins 1 and 2 (cIAP1/2), melanoma-inhibitor of apoptosis (ML-IAP), and inhibitor of apoptosis-like protein-2 (ILP2)." (PMID 36499442, 2022). "In some melanoma cells, knocking down XIAP or survivin (an IAP) seems to be very potent in overcoming the resistance to TRAIL." (PMID 34299249, 2021). "Upregulation of XIAP is also one of the mechanisms in TRAIL-resistant melanoma to prevent apoptosis, which can be counteracted by SMAC/Diablo." (PMID 34299249, 2021).
melanoma (continued). "The effects of our top-ranked molecules were first tested on A375, a melanoma cell line expressing high levels of XIAP, and a Jurkat T-lymphoma cell line expressing high levels of Bcl-2." (PMID 32587235, 2020). "XIAP is overexpressed in leukemia, lung, colon, melanoma, ovarian, bladder, renal, breast, prostate, and thyroid carcinomas." (PMID 32182843, 2020). "Inducible TRAIL resistance in melanoma can be explained by (i) high levels of antiapoptotic Bcl-2 proteins, (ii) high levels of XIAP, and (iii) suppressed Bax activity." (PMID 31083589, 2019). "Herein, it was found that PTX-treated MDA-MB-231 BCA and MDA-MB-435 melanoma cells showed upregulation of IL-6, IL-8 and XIAP expression compared to untreated cells." (PMID 29486738, 2018). "Birinapant also promotes apoptosis by binding to and antagonizing XIAP (IAP proteins X chromosome-linked IAP) and ML-IAP (melanoma IAP), which block apoptosis by suppressing the activity of caspases." (PMID 29520231, 2018). "Here, we provide evidence that alterations in the abundance of the NFκB and XIAP proteins change the sensitivity of resistant melanoma cells to IZI1551 treatment." (PMID 30416750, 2018). "Following these predictions, we confirmed that NFκB inhibition by ectopic expression of IκBα-SR mutant partially reduced cellular XIAP levels in conditioned melanoma cells coinciding with partial re-sensitization to IZI1551." (PMID 30416750, 2018). "To that effect, we showed co-stimulation with the SMAC mimetic SM83 to fully re-sensitize melanoma cells to IZI1551 that had acquired secondary resistance to the TRAIL-agonist via XIAP depletion." (PMID 30416750, 2018). "Comparing IZI1551-sensitive to IZI1551-resistant melanoma cells the model accurately and correctly predicted activation of NFκB in concert with upregulation of the anti-apoptotic protein XIAP as the key mediator of IZI1551 resistance." (PMID 30416750, 2018). "In fact, in late melanoma stage, NF-κB is up-regulated and inhibits cell apoptosis by enhancing the expression of several anti-apoptotic genes such as XIAP, c-FLIP, and BclxL genes." (PMID 28289382, 2017). "They demonstrate that inhibition of NF‐kB by the inhibitor of nuclear factor kappa‐B kinase (IKK) inhibitor Bay 11‐782 or knockdown of XIAP induces melanoma apoptosis in cells exposed to imiquimod." (PMID 26578344, 2016). "High levels of MAPK and/or PI3K signaling typical in melanoma increase levels of anti-apoptotic Bcl-2, Mcl-1, Bcl-XL, survivin and XIAP while suppressing expression of the potent apoptotic inducer Bim and sequestering pro-apoptotic Bmf to the cytoskeleton." (PMID 26426052, 2015). "We have shown previously that pan-HDAC inhibitors can induce apoptosis in melanoma that is associated with upregulation of BIM, BAX and BIK and downregulation of Bcl-XL and XIAP." (PMID 26087189, 2015). "This indicates that XIAP is rather more critical as cIAPs for cell death resistance in melanoma cells." (PMID 26355347, 2015). "Among them, cellular IAP1 (cIAP1), cIAP2, X-linked inhibitor of apoptosis (XIAP), melanoma-IAP (ML-IAP), and survivin have been most extensively characterized." (PMID 24478984, 2014). "In particular, the ability of dinaciclib to regulate these anti-apoptotic proteins is likely to be of great utility in melanoma where overexpression of XIAP, Bcl-2 and Mcl-1 is commonplace and can contribute to melanoma chemoresistance." (PMID 23527225, 2013). "Proving the potency of XIAP as a major inhibitor of TRAIL-induced apoptosis in melanoma cells, its overexpression strongly diminished TRAM/TRAIL-induced apoptosis by 60–70%, as compared to mock-transfected cells." (PMID 22723988, 2012). "Its decisive role for TRAM/TRAIL-induced apoptosis in melanoma cells was further supported by XIAP overexpression, which diminished apoptosis by 50%." (PMID 22723988, 2012). "Melanoma cell lines revealed significant expression of cIAPs as survivin, cIAP-2 and XIAP as well as of the cIAP antagonist SMAC." (PMID 22723988, 2012).
melanoma (continued). "We have recently shown that siRNA mediated down regulation of XIAP sensitizes melanoma cells to TRAIL induced cell death, implying an important role of XIAP." (PMID 23029050, 2012). "In conclusion, SMAC-mimetics targeting members of the IAP family, especially XIAP, offer a new strategy for the treatment of chemotherapy-resistant melanomas, particularly when used in combination with other drugs like Bortezomib, TRAIL or TRAIL-R agonists." (PMID 20461078, 2010). "We show that in melanoma cell lines, which are typically resistant to chemotherapeutic agents, XIAP knock-down sensitises cells to TRAIL treatment in vitro, also favouring the accumulation of cleaved caspase-8." (PMID 20461078, 2010). "In this study, we show that human melanoma cell lines can be sensitised to TRAIL in vitro by knocking down XIAP by shRNA interference." (PMID 20461078, 2010). "It is known that Smac peptide acts not only on XIAP but also on other IAP family members: melanoma IAP, survivin, cIAP1, and cIAP2, the last three being expressed in RCC and their expression confirmed in Caki1 cells." (PMID 18283311, 2008). "Here we assessed XIAP expression in melanomas, using tissue microarrays containing 436 melanomas and 336 nevi by a novel method of automated, quantitative analysis (AQUA)." (PMID 17257402, 2007). "Phenoxodiol can sensitize melanoma cells to Carboplatin in vitro with corresponding XIAP degradation, although the precise target and mechanism of action of Phenoxodiol are subject to further assessment." (PMID 17257402, 2007). "We then assessed a panel of melanoma cell lines for XIAP expression, and found high expression in all cell lines." (PMID 17257402, 2007). "In summary, our studies show that XIAP is up-regulated in melanoma specimens compared to nevi, and expression of XIAP is higher in metastatic than in primary melanomas." (PMID 17257402, 2007). "Finding significantly higher expression in melanoma than in nevi was encouraging for development of XIAP-targeting therapies in melanoma." (PMID 17257402, 2007). "We conclude that XIAP levels in clinical specimens are significantly higher in melanomas than their benign counterparts, and higher in metastatic than in primary specimens, suggesting an association with malignant progression and disease aggression." (PMID 17257402, 2007). "XIAP expression was significantly higher in melanomas than nevi (P < 0.0001), and higher in metastatic than primary lesions (P < 0.0001)." (PMID 17257402, 2007). "Down-regulation of XIAP in melanoma cells by siRNAs sensitizes these cells to TRAIL-induced apoptosis." (PMID 17257402, 2007). "In our large cohort of melanomas and nevi we show significantly higher expression in tumors than in nevi, and XIAP expression was significantly higher in metastatic specimens than in primary melanomas." (PMID 17257402, 2007). "We used S100 to define pixels as melanoma (tumor mask) within the array spot, and measured XIAP expression using Cy5-conjugated antibodies within the mask." (PMID 17257402, 2007). "To assess for intra-tumor heterogeneity of XIAP expression in melanoma specimens, we used tissue arrays containing tumor cores from 565 melanoma patients." (PMID 17257402, 2007). "Based on this fact, it can be hypothesized that the anti-apoptotic proteins XIAP, cIAP1, and cIAP2 are important for melanoma survival." (PMID 41465443, 2025). "Therefore, identifying more durable and efficient inhibitors of XIAP, especially through combined dual-target approaches, is crucial for advancing melanoma therapy." (PMID 40486906, 2025). "In A375 melanoma cells, the second mitochondria-derived activator of caspases (SMAC) promotes apoptosis by interacting with LATS1, leading to the degradation of X-linked inhibitor of apoptosis protein (XIAP) in metastatic malignant melanoma." (PMID 41550920, 2025).
melanoma (continued). "Furthermore, Western blot analysis of the NTC-shRNA group revealed that TRI-03 treatment led to decreased levels of XIAP in melanoma tissue, as well as increased cleavage of GSDME and caspase-3." (PMID 40486906, 2025). "Kluger found that the novel isoflavone derivative phenoxodiol induced apoptosis by restraining the expression of X-linked inhibitor of apoptosis protein (XIAP) in melanoma cells, and melanoma YUMAC cells exposed to phenoxodil for 4 h displayed a decrease in the level of XIAP." (PMID 38586368, 2024). "However, emerging in vitro and in vivo evidence in attributes XIAP a role in neutrophil attraction through IL-8 and subsequent melanoma progression." (PMID 38419052, 2024). "Among the eight described mammal homologs, XIAP (X-linked IAP), cIAP1 (cellular IAP1), cIAP2, ML-IAP (Melanoma IAP) and ILP-2 (IAP-like protein 2) are enzymes of the ubiquitination reaction involved in proteostasis and the regulation of the assembly of intracellular signaling platforms." (PMID 35204822, 2022). "X-linked inhibitor of apoptosis protein (XIAP) is an inhibitor of apoptosis protein highly expressed in melanoma, and we found that its expression level was not affected by circ_0084043 and miR-134-5p." (PMID 36387162, 2022). "As chemotherapy primarily eliminates cancer cells by apoptosis, we here evaluated if the expression of key apoptosis regulators (Bax, Bak, Bcl-2, Bcl-xL, Smac, Procaspase-9, Apaf-1, Procaspase-3 and XIAP) allows prognosticating PFS in stage III/IV melanoma patients." (PMID 32054850, 2020). "In melanoma cells, XIAP seems to play this particular role in TRAIL sensitization." (PMID 31083589, 2019). "This became even more evident when we could correlate elevated XIAP expression level in melanoma cells to intrinsic TRAIL resistance, indicating that XIAP may serve as a biomarker for TRAIL responsiveness of mutBRAF melanoma." (PMID 30416750, 2018). "Interestingly, caspase-3-dependent cleavage of XIAP, followed by its proteasomal degradation, has been shown to accompany cisplatin-mediated sensitization of melanoma cells to TRAIL-induced apoptosis." (PMID 29182622, 2017). "Similarly in melanoma cell lines, the inhibition of NF-κB resulted in decreased XIAP expression and induction of apoptosis." (PMID 23720710, 2013). "Furthermore, in melanoma cells depletion of endogenous XIAP promoted apoptosis and reduced clonogenicity of cancer cells treated with cisplatin." (PMID 23720710, 2013). "This hypothesis is strengthened by other data showing that the silencing of Bcl2, FLIP or IAPs (XIAP and survivine) by siRNAs sensitizes resistant melanoma cells to TRAIL-induced apoptosis." (PMID 22136382, 2011). "Thus, XIAP contributes to the resistance of melanoma cells to TRAIL and its downregulation favours the extrinsic apoptotic pathway." (PMID 20461078, 2010). "This is the first study of XIAP expression in a large cohort of melanoma specimens." (PMID 17257402, 2007). "We found significantly higher expression levels of XIAP in melanomas than in benign nevi." (PMID 17257402, 2007). "We studied XIAP expression in a panel of melanoma cell lines by Western blot analysis." (PMID 17257402, 2007). "However, to the best of our knowledge, there are no large cohort studies that thoroughly assess expression levels of XIAP in specimens from patients with melanoma." (PMID 17257402, 2007). "Melanoma resistance to Carboplatin is possibly due to XIAP over-expression." (PMID 17257402, 2007). "Furthermore, we demonstrate that degradation of XIAP by Phenoxodiol confers Carboplatin sensitization in melanoma cells." (PMID 17257402, 2007). "Furthermore, the expression of proapototic protein XAF1, which blocks the XIAP-mediated inhibition of caspase-3, is also reduced in human melanomas." (PMID 16755297, 2006).